BRCA1 (BRCA1 DNA repair associated)
Diseases named in the same sentence as BRCA1 in open-access papers (continued):
Sharing a sentence is not in itself a finding about the gene and the disease.
prostate carcinoma (continued). "Moreover, in the ATM, BRCA1 and BRCA2 genes from prostate cancer patients, the distributions of germline benign, pathogenic, VUS, and recurrent somatic variants differ across Pfam domains." (PMID 34253785, 2021). "Germline BRCA1/2 mutations associated with HRD are clinical biomarkers for sensitivity to poly-ADP ribose polymerase inhibitors (PARPi) treatment in breast, ovarian, pancreatic, and prostate cancers." (PMID 34572800, 2021). "The potential that genomics has brought to biomarker testing in diagnosis, prediction and research is being realised, pre-eminently in many cancers, but also in an ever-wider range of conditions-notably BRCA1/2 testing in ovarian, breast, pancreatic and prostate cancers." (PMID 33540773, 2021). "In breast and prostate cancer cells, knockdown of BRCA1 enhanced CSC characteristics." (PMID 34638302, 2021). "In male BRCA1/2 PVs carriers, prostate cancer is the most commonly diagnosed cancer." (PMID 34298749, 2021). "Genetics of prostate cancer have shown population specific features, particularly related mutations in HOXB13, NBN, and CHEK2; however mutations in BRCA2, mismatch repair genes, BRCA1, and ATM appear to contribute to risk in many populations." (PMID 34503195, 2021). "A recent meta-analysis on BRCA-associated prostate cancer risk and mortality also reported an increased mortality in BRCA2 carriers and concluded that BRCA2 but not BRCA1 mutations were associated with higher prostate cancer mortality." (PMID 34575694, 2021). "We consider it to be inappropriate to treat a woman with DCIS or a man with prostate cancer expectantly without first ruling out a BRCA1 or BRCA2 mutation." (PMID 33920818, 2021). "Poly (ADP-ribose) polymerase (PARP) inhibitors, for example, are used for BRCA1/2-positive breast, ovarian, and pancreatic cancer and have been FDA approved in the United States for castration-resistant ATM-deficient prostate cancer following a recent clinical trial." (PMID 34262154, 2021). "These cancers may also be relevant in investigating genes that confer lifetime risks of prostate cancer, such as BRCA1 and BRCA2." (PMID 32948129, 2020). "In this study we followed unaffected men known to carry mutations in the BRCA1 and BRCA2 genes to investigate whether they are at higher risk of developing prostate cancer compared to the general population." (PMID 31495749, 2020). "Since then, many examples of secondary mutations in BRCA1/2, as well as RAD51C, RAD51D, and PALB2, that genetically revert the mutation and restore functional full-length protein have been reported in breast, ovarian, pancreatic, and prostate carcinoma." (PMID 32029455, 2020). "BRCA1/2-deficient prostate cancers not only show increased sensitivity to platinum-based chemotherapies, but also to poly-(ADP-ribose) polymerase (PARP) inhibitors, thus giving BRCA1/2 deficiency a high clinical relevance in these patients." (PMID 31549213, 2019). "Interestingly, EZH2 and BRCA1 are coregulated in primary prostate cancer cells and cooperate in the regulation of CSC phenotype and properties." (PMID 31366128, 2019). "Deleterious BRCA1 or BRCA2 mutations may also moderately increase the risk of breast and prostate cancer in men, and pancreatic cancer or colorectal cancer in both sexes." (PMID 30518089, 2018). "Additionally, the IGF-I/IGF-IR signalling pathway negatively correlates with BRCA1 abundance in breast and prostate cancer cells, suggesting an interplay between BRCA1 and IGF-I/IGF-IR signalling." (PMID 30323899, 2018). "Across all cancer types, only 45% of bi-allelic alterations in HR-related genes occurred in traditional BRCA1/2-associated hereditary cancers (hereditary breast and ovarian cancer (HBOC), namely breast, ovarian, and prostate cancer), suggesting that this pathway is altered in other malignancies." (PMID 29021619, 2017).
prostate carcinoma (continued). "BRCA2 mutation involves a lifetime risk of developing PC ranging from 30-40%, while BRCA1 mutation carriers present a 3–8% lifetime risk with a modestly elevated incidence of early onset prostate cancer but no increased risk in older men." (PMID 27819754, 2017). "PSA > 3.0 was found to have a 48% positive predictive value for prostate cancer in the BRCA2 population compared to 24% in controls who were not carriers of BRCA1/2 mutations." (PMID 28946846, 2017). "For carriers of BRCA1 mutations, men at the 5th percentile of the prostate cancer PRS have a 7% risk of developing prostate cancer by age 80, and men at the 95th percentile of the PRS distribution have a prostate cancer risk of 26%." (PMID 28448241, 2017). "For example, on the basis of the prostate cancer PRS, 43% of men with BRCA1 mutations are predicted to have a prostate cancer risk of greater than 17% and may benefit from enhanced screening, whereas those at lower risk may opt for more limited surveillance." (PMID 28448241, 2017). "Several groups have shown that BRCA1 and 2 mutation carriers have a more aggressive form of prostate cancer than those without the mutation, and also have a worse prognosis." (PMID 28031937, 2016). "While BRCA1, FANCG and RAD51 have previously been linked to various treatment responses in a number of cancers limited research exists investigating the association between RT-induced regulation of these genes in radiation resistant prostate cancer." (PMID 25369795, 2014). "The same group also demonstrated shorter TL in both sporadic and hereditary ovarian cancer compared with controls; no similar investigation has been carried out in male BRCA1/2 mutation carriers with prostate cancer." (PMID 24489760, 2014). "The significance of the presence of the 17q25.3 amplification in prostate cancer in relation to BRCA1 deficiency is not clear." (PMID 25416589, 2014). "Targets within this pathway could provide strategies for modulation of PTEN/BRCA1 proteins, which may prove therapeutically beneficial for breast, ovarian, and prostate cancer treatment." (PMID 25426449, 2014). "However, the familial modifying effects for CHEK2 on the risks of breast, colon and prostate cancer observed here were more extreme than those seen in our earlier studies of BRCA1 carriers." (PMID 19401704, 2009). "Therefore, we expect the survival experience of men with prostate cancer in BRCA1 families to be similar to that of the general population." (PMID 18577985, 2008). "GADD45A found downregulated in prostate cancers in our study is a well-established BRCA1 target." (PMID 17280610, 2007). "There are no guidelines for the risk management of men with BRCA1/2 mutations although research is underway (IMPACT: targeted screening for prostate cancer)." (PMID 17285126, 2007). "BRCA1 and BRCA2 have been identified as tumour suppressors for several different hormone-responsive cancer types (breast and prostate cancers (BRCA1 and BRCA2) and endometrial and cervical cancer (BRCA1)) and a non-endocrine cancer type (pancreas cancer (BRCA1 and BRCA2))." (PMID 16434996, 2006). "We tested for the BRCA1 185delAG frameshift mutation, found in 0.9% of Ashkenazi Jews, and the BRCA2 6174delT mutation, found in 1% of Ashkenazi Jews, in Ashkenazi Jewish men with prostate cancer." (PMID 9743298, 1998). "The contribution of germline BRCA1 and BRCA2 mutations to prostate cancer incidence is probably small and could be limited to specific subgroups." (PMID 9743298, 1998). "The association with BRCA1/2 pathogenic variants for aggressive and nonaggressive prostate cancer." (PMID 41423785, 2026). "In prostate cancer, the PROfound and TALAPRO-2 trials demonstrated that PARP inhibitors significantly improve outcomes in patients with metastatic castration-resistant disease and homologous recombination repair alterations, with the most pronounced benefit observed in those with BRCA1/2 mutations." (PMID 41487567, 2025).
prostate carcinoma (continued). "BRCA1 gene expression was significantly downregulated in methylated tumor samples as compared to non-methylated tumors and normal tissues, which suggested that promoter hypermethylation of the BRCA1 gene could serve as a viable biomarker for prostate cancer." (PMID 40075848, 2025). "Notably, early investigations in Ashkenazi Jewish hereditary prostate cancer pedigrees reported no enrichment of BRCA1/2 founder mutations, underscoring population-specific genetic architectures." (PMID 41440226, 2025). "Therefore, exploring the interrelationships of BRCA1 or BRCA2 with other genes and pathways may offer further assistance in the treatment of BRCA mutation-associated prostate cancer." (PMID 39917165, 2025). "Therefore, patients with prostate cancer and pathogenic variants of BRCA1/BRCA2 or ATM are not appropriate candidates for active surveillance, even if other clinical and pathological features are acceptable." (PMID 37174127, 2023). "Fifteen variants in BRCA1 and 28 variants in BRCA2 were filtered out due to insufficient evidence in ClinVar, with a high fraction (47% and 71%, respectively) identified on-tumor (i.e., in breast/ovarian/pancreatic/prostate cancers), as expected for true pathogenic germline variants." (PMID 37568048, 2023). "Therefore, PARPi initially was approved for solid tumors with BRCA1/2 dysfunction, such as ovarian, breast, and prostate cancers, instead of hematologic malignancies lacking BRCA1/2 mutation." (PMID 37442994, 2023). "In August 2023, niraparib (not yet approved for prostate cancer) was approved in combination with abiraterone for the treatment of patients with deleterious or suspected deleterious BRCA1- or BRCA2-mutated mCRPC, based on the findings of the MAGNITUDE trial (NCT03748641)." (PMID 37829336, 2023). "Although molecular alterations in HRR genes besides BRCA1/2 are less established surrogate markers for HRD, mutations in ATM and PALB2 but not in other HRR genes were shown to be associated with sensitivity to PARPi in prostate carcinoma in a phase 3 clinical trial." (PMID 36779660, 2023). "In addition to the essential analysis of BRCA1/2 mutations, which included the detection of large deletions and complex mutations, the assay also allows for mutation detection of known HRR genes, which have been found to be relevant to prostate cancer." (PMID 37444554, 2023). "The lower odds ratios for the breast and prostate cancer PRS in male BRCA1 and BRCA2 carriers, compared with the general population, may reflect a general attenuation of the effect sizes of common variants on genetic risk in the presence of a pathogenic variant in a high-risk gene." (PMID 34320204, 2022). "It is not clear that BRCA1 predisposes to a more aggressive form of prostate cancer." (PMID 35732815, 2022). "Recently, a large family-based study suggested that BRCA2 P/LPVs are associated with a statistically significant risk for stomach cancer, while associations of BRCA1 P/LPVs carriers with prostate cancer or cutaneous melanoma could not be confirmed." (PMID 36230512, 2022). "In addition to DNA repair pathways, BRCA1/2 also could repress the progression of prostate cancer by inhibiting PI3K/AKT and MAP/ERK pathways, as well as MMP9 and AR signaling." (PMID 35734583, 2022). "The Advanced Prostate Cancer Consensus Conference held in 2019 supported consideration of BRCA1 and BRCA2 testing in screening, management, and informing prognosis/treatment, with germline testing recommended in patients with a tumour BRCA1, BRCA2, or ATM mutation." (PMID 33630412, 2021). "In the near future, male carriers of BRCA1/2 PVs should benefit from PRS cancer risk stratification that might enable these men and their physicians to make informed decisions on the type and timing of breast and prostate cancer risk management." (PMID 34298749, 2021). "Furthermore, there are data suggesting that only BRCA2 but not BRCA1 mutations are associated with high efficacy of PARPi in prostate cancer." (PMID 34454564, 2021).
prostate carcinoma (continued). "A larger cross-sectional analysis of 1328 men with prostate cancer by Giri and colleagues found 15.6% carriers of germline mutations; 10.9% patients carried a mutation in DNA repair genes (BRCA2 > CHEK2 > ATM > BRCA1), increasing the risk of more advanced tumors (Gleason score ≥ 8)." (PMID 33322746, 2020). "The IMPACT study (Identification of Men with a genetic predisposition to ProstAte Cancer: Targeted Screening in men at higher genetic risk and controls) is an international, multicentre study evaluating the role of targeted PSA screening in men with BRCA1/2 mutations." (PMID 29802810, 2019). "However, until phase III trials are completed, the genes other than BRCA1/BRCA2 that could be considered predictive for PARP inhibitor response in advanced prostate cancer will likely remain unknown." (PMID 31242618, 2019). "We did not detect any somatic BRCA1 mutations in this high-risk prostate cancer patient cohort." (PMID 28676659, 2017). "Hence, the aim of the present study is to determine whether loss of heterozygosity (LOH) in RAD51, BRCA1, and BRCA2 contributes to the sporadic prostate cancer." (PMID 26433958, 2015). "The HR/PARP synthetic lethality model may be more widely applicable in prostate cancer with germline or somatic inactivating mutations in the HR DNA repair genes, CHK2, BRIPI/FANCJ, NBS1, BRCA1, and ATM, collectively thought to occur in 20–25% of prostate cancer cases." (PMID 24616882, 2014). "No prostate cancers were observed in relatives of BRCA1 mutation carriers." (PMID 20877337, 2010). "In contrast, the BRCA1 carriers in that study were not at increased risk of prostate cancer." (PMID 18577985, 2008). "Individuals with pathogenic BRCA variants face an elevated risk not only for breast and gynecologic cancers but also for pancreatic cancer (BRCA1: 1–3%, BRCA2: 3–5% by age 70), and male carriers for prostate cancer (BRCA1: 21%, BRCA2: 27% by age 75)." (PMID 41528496, 2026). "A similar observation was made regarding the family history of prostate cancer, which was present in 25% of BARD1 carriers compared to only 2.4% of BRCA1 carriers (p-value = 0.005)." (PMID 40805222, 2025). "BRCA1 and BRCA2 have emerged as critical biomarkers in advanced prostate cancer, given their essential roles in homologous recombination repair and genomic stability." (PMID 40725150, 2025). "BRCA1 exon 22 and BRCA2 exon 27 have been reported in advance prostate cancer pathogenesis due to homologous recombinant repair defects." (PMID 40725150, 2025). "BRCA1/2 CNV detection was performed on DNA samples from 7 healthy individuals and 11 advanced prostate cancer patients." (PMID 40725150, 2025). "We also found increased CBC and prostate cancer risks in male BRCA2 PV carriers and elevated colorectal and pancreatic cancer risks in female BRCA1 and BRCA2 PV carriers." (PMID 39475295, 2025). "In prostate cancer, MYCN enhances tumor progression by transcriptionally activating genes such as PARP1 and BRCA1." (PMID 40593489, 2025). "In BRCA1/2-mutant HGSOC and BRCA2/ATM-mutant prostate cancer, M2 macrophages exhibit a preferential accumulation within regions of proliferating tumor cells." (PMID 40830526, 2025). "Overall, the high sensitivity and precision of ddPCR make it a robust platform for clinical BRCA1/2 CNV testing, enabling improved biomarker detection and supporting personalized treatment strategies in advanced prostate cancer." (PMID 40725150, 2025). "Recommendations tend to range from targeted gene tests for one or two genes (BRCA1/2) to a prespecified gene panel (e.g. HRR and/or MMR genes), or large panel testing for advanced prostate cancer." (PMID 37202470, 2024).
prostate carcinoma (continued). "BRCA1 and BRCA2 sequencing data obtained from tissue somatic DNA of prostate cancer patients were analyzed." (PMID 39335746, 2024). "On the basis of the most relevant literature results, we describe an overview of our NGS BRCA1 and BRCA2 data of prostate cancer patients’ FFPE samples, and we highlight technical procedures performed and relevant clinical implications." (PMID 39335746, 2024). "Here, we report an overview of CGP results, specifically of BRCA1 and BRCA2 HRD-repair system genes, from patients with prostate cancer analyzed in our institution, and we compare our results with those available from more recent scientific literature." (PMID 39335746, 2024). "In a molecular analysis of 333 primary prostate cancers, the Cancer Genome Atlas (TCGA) study showed a 19% prevalence of alterations in several DNA repair genes, including BRCA2, BRCA1, ATM, CDK12, FANCD2, and RAD51C." (PMID 37240284, 2023). "Several tumor types, particularly breast, ovarian, pancreatic, and prostate cancer, exhibited a strong correlation between elevated gLOH and biallelic alterations in multiple key HRR genes beyond BRCA1 and BRCA2." (PMID 38201431, 2023). "One of the pathways often altered in advanced prostate cancer is DNA damage response (DDR), including alterations in BRCA1/2 and other homologous recombination repair (HRR) genes." (PMID 37434977, 2023). "It has been revealed that DDR genes alterations including BRCA2, BRCA1, CDK12, ATM, FANCD2, or RAD51C affect almost 20% of 333 primary prostate cancer." (PMID 36739400, 2023). "Data regarding genomic alterations in populations of prostate cancer patients in SSA was minimal, including data on frequency of BRCA1, BRCA2 or other homologous recombination repair genes." (PMID 37368872, 2023). "Furthermore, the targeted inhibition of DNA repair machinery notably using PARP inhibitors (e.g., Niraparib, Veliparib and Olaparib, currently tested with BRCA1/2mut breast, ovarian and prostate cancers 60, 61) could be especially beneficial for treating HPV-positive cancer patients." (PMID 36793865, 2023). "In prostate cancer cell lines, the combination was shown to suppress the p-Rb1-E2F1 signalling axis leading to inhibition of E2F1 gene targets such as BRCA1/2 and RAD51 among others." (PMID 37430137, 2023). "In a large dataset of 7,707 men with advanced prostate cancer undergoing comprehensive genomic profiling (CGP) of cell-free DNA (cfDNA), 614 men harbored BRCA1 and/or BRCA2 alterations." (PMID 36185208, 2022). "As such, we decided to generate CRISPR-mediated BRCA1 or BRCA2 gene KOs in the ovarian adenocarcinoma cell line SKOV3 and the prostate carcinoma DU145 cell line." (PMID 36969741, 2022). "Germline BRCA1 and BRCA2 PVs increase the developing prostate cancer with a higher likelihood of aggressive disease for BRCA2 PV carriers." (PMID 35563100, 2022). "The prevalence of HRR alterations in prostate cancer is approximately 25%; however, understanding of prognostic and therapeutic implications of different HRR alterations beyond BRCA1/2 is currently limited due to small patient cohorts." (PMID 36497408, 2022). "Poly (ADP-ribose) polymerase (PARP) inhibitor (PARPi) studies in prostate cancer (PCa) have focused primarily on the homologous recombination repair (HRR) genes, specifically BRCA1 and BRCA2." (PMID 36230674, 2022). "The predicted absolute risks of developing prostate cancer by age 85 years were 13.1% at the 5th and 50.4% at the 95th PRSPC distribution percentiles for BRCA1 carriers." (PMID 34320204, 2022). "BRCA1 differentially regulates IGF-IR expression in androgen receptor (AR)-positive and AR-negative prostate cancer cells." (PMID 36010882, 2022). "Forced expression of LMNB1 in prostate cancer cells increased the mRNA level of several HRR genes, especially BRCA1." (PMID 35241075, 2022).